TNF (tumor necrosis factor)
Diseases named in the same sentence as TNF in open-access papers (continued):
Sharing a sentence is not in itself a finding about the gene and the disease.
oral cancer (106 papers, 2012 to 2025). "Upregulation of LINC00944 in EBV-associated OSCC contributes to oral cancer progression by promoting migration and invasion through one of its functions as ceRNA, which targets specific miRNAs that regulate proteins in the TNFα/NF-κB signaling pathway." (PMID 39941858, 2025). "TGF-β, SMAD2, TNFα, and NFκB downregulation was associated with a decrease in oral cancer cell movement." (PMID 39156270, 2024). "The presence of mucosal white lesions associated with elevated levels of inflammatory biomarkers such as IL-6, IL-8, IL-1 beta, and TNF-alpha suggests a heightened risk of oral cancer." (PMID 39097712, 2024). "GSEA of CAFs activated by oral cancer-derived EVs revealed upregulation of several pathways linked to inflammation including TNFα, IL6_JAK_STAT3 pathway, and IL2_STAT5 signaling pathway." (PMID 37745296, 2023). "Overall, the passage highlights the potential diagnostic value of IL-8, IL-6, and TNF-α as biomarkers for oral cancer and the upregulation of PTHLH/PTHrP in various tumors, including OSCC." (PMID 38067304, 2023). "TNF- α and IL-6 was evaluated in Oral Leukoplakia against controls and was found to reveal an increased expression of TNFαin association with Oral cancer and in Oral Potentially Malignant Disorders.The concentration of TNFα had a bearing on its function." (PMID 36518124, 2022). "Functional polymorphisms affecting gene expression of IL-4,-6,-8,-10 and TNF have been shown to strongly associate with increased risk for oral cancer." (PMID 35844493, 2022). "Inhibition of TNFα or Schwann cell activation will provide potential treatments for oral cancer and associated pain." (PMID 33469141, 2021). "TNFα overexpression has been reported in tumor tissues, blood, and saliva samples of oral cancer patients; TNFα overexpression is associated with reduced overall survival and disease-free survival of oral cancer patients." (PMID 33469141, 2021). "The present study proved the clinical significance of TNF-α and micronuclei in oral cancer screening of high-risk patients." (PMID 34299679, 2021). "In this study, we are mainly focusing on largely associated oral cancer pain mediators TNF-alpha, IL-8, and endothelin secreted by oral tumor cells and cancer stem cells and the effect of allicin in reducing these pain mediators." (PMID 34071008, 2021). "TNF – α, a widely expressed pro-inflammatory cytokine, has been shown diagnostic utility in oral cancer and is found more abundant in saliva compared to that in serum." (PMID 31350970, 2019). "The frequency of “A” allele also positively correlates with high TNF-α levels in patients with oral cancer." (PMID 28881857, 2017). "TNF-α has been linked to radioresistance of oral cancer cells whereas IFN-γ is able to induce cathepsin S expression which leads to radioresistance." (PMID 25005804, 2014). "Oral cancers are associated with inflammatory mediators, such as IL-6 and TNF, which potentially exert their effects through dual mechanisms, namely, by enhancing the extravasation of albumin across the capillary endothelium at the tumor site and dampening the hepatic production of albumin." (PMID 38476986, 2024). "Inhibiting TNFα or Schwann cell activation might serve as therapeutic approaches for the treatment of oral cancer and associated pain." (PMID 33469141, 2021). "Our results are consistent with previous findings where increased levels of NF-κB associated IL-6, IL-8, and TNF-α in oral cancer saliva have been reported, suggesting that OSCC progression is likely enhanced by continued expression of pro-inflammatory and pro-angiogenic cytokines." (PMID 33924500, 2021). "Tumor necrosis factor alpha (TNF-α) polymorphisms are frequently noted in oral cancer research." (PMID 24278120, 2013).
oral cancer (continued). "The proangiogenic and pro-inflammatory cytokines IL-1, IL-6, IL-8 and TNF-α are elevated in saliva samples of patients with oral cancer and oral precancer, so they have the potential of surrogate indicators of carcinogenic mutation from oral precancer to oral cancer." (PMID 35888762, 2022). "Science demonstrates extensive use of saliva-based testing forsystemic and local diseases such as oral cancers resulting in successful detection of IL-6, IL-8, TNF-α cytokines." (PMID 40978585, 2025). "In a previous study, miRNA-21 was shown to induce TNF-α expression in patients with oral cancer, enhancing tumor progression." (PMID 41614883, 2025). "IL-37 attenuates the proliferation of oral cancer cells induced by lipopolysaccharide and tumor necrosis factor-alpha, while knockdown of IL-37 exacerbates this induction." (PMID 40444012, 2025). "Candida infection induces cytokines like IL8 and TNF-a, which stimulate TLRs that can interact with the NF-kB inflammatory process in oral cancer metastasis." (PMID 40126352, 2025). "Although we have not determined the specific nociceptive mediators released by Schwann cells following TRPV4 activation, previous studies suggest the involvement of IL-6, CX3CL1, and TNF-α from Schwann cells in oral cancer pain." (PMID 40144515, 2025). "This study observed that the STAT3 inhibitor stattic robustly compromised TNF-α-induced upregulation of inflammation-related genes in oral cancer cells, emphasizing the significant role of IL-37 in modulating inflammation in these cells." (PMID 40444012, 2025). "Collectively, these findings demonstrate that KD of IL-37 exacerbates the LPS- and TNF-α-induced proliferation and migration of oral cancer cells." (PMID 40444012, 2025). "F. nucleatum promotes the production of cytokines, including TNF, IL-6, 8, 10, and 12, as well as ROS and kinase, which enhance the progression of oral cancer." (PMID 40126352, 2025). "Salivary protein biomarkers for the early diagnosis and prevention of oral cancer include IL-8, IL-6, and tumor necrosis factor α (TNF-α)." (PMID 40096320, 2025). "Collectively, these findings demonstrate that IL-37 effectively mitigates the proliferation and migration induced by LPS and TNF-α in oral cancer cells." (PMID 40444012, 2025). "Our findings highlight the crucial role of the oral microbiome in regulating key metabolic enzymes, such as CPT1A and OXSR1, as well as cytokines like TNF-α and IL-6 in oral cancer." (PMID 39456670, 2024). "The presence of TNF-α within the diseased environment makes it a dependable prognostic agent for detecting oral cancer." (PMID 38406163, 2024). "We discovered that naringin treatment dramatically reduced TGF-β, SMAD2, TNFα, and NFκB gene expression in oral cancer cells." (PMID 39156270, 2024). "We then examined the mRNA expression of transforming growth factor-beta (TGF-β), suppressor of mothers against decapentaplegic 2 (SMAD2), tumor necrosis factor alpha (TNFα), and nuclear factor kappa B (NFκB) signaling molecules in oral cancer cell lines." (PMID 39156270, 2024). "The anomalous activation of TGF-β, SMAD2, TNFα, and NFκB signaling in oral cancer cells can encourage the growth and spread of tumors." (PMID 39156270, 2024). "Elevation of inflammatory mediators, including tumor necrosis factor-alpha (TNF-α) and interleukin-6 (IL-6), has promoted cellular proliferation, inhibited apoptosis, and fostered oral cancer progression through complex signaling pathways." (PMID 38435153, 2024). "Capsaicin treatment significantly reduced the expression of the anti-apoptotic genes TNFα and NFκB in oral cancer cells." (PMID 39435241, 2024). "Considering TNFα signaling via NF-κB, TNFα promotes oral cancer proliferation, progression, and nociception at least partially by activating Schwann cells." (PMID 38287071, 2024). "This study investigated the effects of capsaicin on oral cancer cell lines, with a particular emphasis on the TNFα and NFκB signaling pathways." (PMID 39435241, 2024).
oral cancer (continued). "Veillonella parvula is elevated in oral cancer, especially in oral squamous cell carcinoma, by promoting the expression of inflammatory cytokines, including interleukins (IL-6, IL-8) and TNF-α." (PMID 39410033, 2024). "The study highlights capsaicin's potential as a cytotoxic and pro-apoptotic phytochemical that affects TNFα and NFκB gene expression, underscoring its promise as a therapeutic agent for oral cancer." (PMID 39435241, 2024). "Several inflammatory mediators, salivary proteins, and oral microbiota are shared between inflammatory conditions of the oral cavity (IL-1, IL-6, IL-8, TNF-α), such as periodontitis, and oral cancer." (PMID 37686542, 2023). "Pro-inflammatory mediators, such as interleukin (IL)-6, IL-8, and tumour necrosis factor (TNF)-α, have been demonstrated to be elevated in oral cancer patients." (PMID 36980727, 2023). "Overexpression of TNF-α in HNSCC is associated with higher proliferative potency, and inhibiting TNF-α in oral cancer suppressed tumor growth." (PMID 37711747, 2023). "Studies have shown that TNFα induces activation of the NF-κB pathway in OSCC cell lines, causing increased motility and invasiveness and inducing EMT in oral cancer cells, playing a key role in the development of metastases." (PMID 36769105, 2023). "One of the main etiological factors in OPMDs and oral cancer is the habit of smoking, and the decreased uric acid levels in the present study may be due to oxidative stress and the formation of oxygen radicals that cause the production of interleukin-1 (IL-1), IL-6, and TNF." (PMID 37378204, 2023). "For instance, certain inflammatory cytokines, such as IL-8, IL-6, and TNF-α, have been identified as potential biomarkers for diagnosing oral cancer." (PMID 38067304, 2023). "Pro-inflammatory cytokine (IL-1, IL-6, IL-8 and TNF- Alpha) and anti-inflammatory cytokine (IL-4, IL-10 and IL-13) levels are higher in individuals with oral cancer." (PMID 36005252, 2022). "IL-8 influences cell proliferation and angiogenesis, but TNF alpha is responsible for cell survival, apoptosis and proliferation, which, overall, are involved in oral cancer development." (PMID 36005252, 2022). "In oral cancer cells and monocytes, the expression of TNF-α and CCL2 was increased after HAR1A knockdown and decreased after ALPK1 knockdown." (PMID 36139553, 2022). "Salivary cytokine levels, including IL-8, IL-6, and TNF-α, can be potential biomarkers for oral cancers." (PMID 35740551, 2022). "TNF also plays additional roles in promoting tumorigenesis and is overexpressed in human oral cancer tissues." (PMID 35844493, 2022). "This was corroborated by various articlesemphasizing the key role of TNFα in the various inflammatory pathways leading onto periodontal destruction, a biomarker of Oral cancer and OPMDs and other systemic diseases." (PMID 36518124, 2022). "We examined the effect of TNFα inhibition on cancer growth, Schwann cell activation, and pain-like behaviors using cell culture and animal models of oral cancer." (PMID 33469141, 2021). "TNF-α has been identified in detectable concentrations in saliva but has been studied only in patients with oral cancers and inflammations." (PMID 34063278, 2021). "The TNFα concentration in resected oral cancer tissues was significantly higher than anatomically matched healthy tissues from the same patients." (PMID 33469141, 2021).
oral cancer (continued). "Further, TNFR1 knockdown has been shown to result in a decrease in oral cancer cell line invasion and inhibition of TNFα-induced invadopodia formation." (PMID 34650923, 2021). "Oral cancer or TNFα alone increases Schwann cell activation (measured by Schwann cell proliferation, migration, and activation markers), which can be inhibited by neutralizing TNFα." (PMID 33469141, 2021). "This is also supported by our recent results that show that neutrophils and TNFα promotes the invasion of oral cancer cells in vitro." (PMID 35048057, 2021). "Regarding the effective concentration, GLY extracts showed an inhibition of TNF-α level in oral carcinoma cells at more than 0.2 mg/mL, cell migration, and MMP-9 production in VSMCs at more than 0.125 mg/mL, and angiogenesis of HUVEC at 1.0–1.5 mg/mL." (PMID 33498415, 2021). "TNFα promotes oral cancer progression in part by regulating proinflammatory cytokines in the cancer microenvironment." (PMID 33469141, 2021). "Since TNFα is known to activate the c-Jun N-terminal kinase (JNK) to cause persistent pain, we measured the analgesic effect of JNK inhibitor, SP600125, on oral cancer-induced mechanical allodynia in the hindpaw." (PMID 33469141, 2021). "TNFα inhibitor C-87 reduced Schwann cell activation and attraction between Schwann cells and oral cancer cells." (PMID 33469141, 2021). "GLY extracts have anti-inflammatory and anti-tumor effects, which suppress TNF-α level in human oral carcinoma cells, angiogenesis in HUVEC, and migration of VSMCs." (PMID 33498415, 2021). "TNFα promotes oral cancer invasiveness and metastasis through autocrine signaling and paracrine signaling between cancer cells and cancer stromal cells in vitro." (PMID 33469141, 2021). "TNFα is overexpressed in oral cancers and correlates positively with self-reported pain in patients." (PMID 33469141, 2021). "In the same line of the observations, the increase of cis-vaccenate would decrease the production of anti-inflammatory palmitoleic acid, leading to the increase of inflammatory cytokines like TNF-alpha required for the oral cancer stemness and aggressiveness." (PMID 34604102, 2021). "Antagonizing TNFα reduces oral cancer proliferation, cytokine production, and nociception in mice with oral cancer." (PMID 33469141, 2021). "Inhibiting TNFα signaling abolished oral cancer-evoked functional allodynia and disrupted T cell infiltration in mice." (PMID 33469141, 2021). "Adding C-87 directly into the oral cancer culture reduced cell proliferation, confirming the role of TNFα autocrine signaling in oral cancer proliferation." (PMID 33469141, 2021). "An in vitro human oral cancer cell line study demonstrated that GLY suppresses TNF-α secretion through NF-κB-, AKT-, and ERK-dependent pathways." (PMID 34200223, 2021). "We demonstrate that TNFα is overexpressed in human oral cancer tissues and correlates with increased self-reported pain in patients." (PMID 33469141, 2021). "We measured TNFα in human oral cancer tissues and correlated TNFα concentration with reported pain scores in patients." (PMID 33469141, 2021). "We demonstrated a positive correlation between TNFα concentration in the tumor and self-reported pain in oral cancer patients." (PMID 33469141, 2021). "Other authors proposed that TNF-α can serve as a biomarker for the early diagnosis of pre-oral cancer, given that the levels of this cytokine and various ILs are higher in patients with more advanced precancerous lesions." (PMID 32708341, 2020). "It has been also found that Hes1 in TNFα-induced oral cancer stemness is the objective of the actuated Notch1 so that its knock-down inhibits self-renewing potential of TNFα-treated OSCC cells." (PMID 32280305, 2020). "There is also a fairly extensive literature, largely from the orient and in dental journals, on the use of analyses for TNF in saliva in diagnosing oral cancer but nothing on its broader application to systemic disease." (PMID 32019214, 2020).
oral cancer (continued). "In our previous studies, we found that TNF-α increased the spontaneous fusion between oral cancer cells and vascular endothelial cells." (PMID 31380426, 2019). "The constraint in the number of studies conducted to detect the actual response of TNF- α limits the knowledge of its role in oral precancer and oral cancer." (PMID 31350970, 2019). "Afterward, we found that the fusion between oral cancer cells and vascular endothelial cells was apparently enhanced in TNF-α-induced inflammatory environment." (PMID 31380426, 2019). "The current study is done to evaluate the efficacy of one such biomarker i.e. TNF- α as an indicator for oral precancer and oral cancer." (PMID 31350970, 2019). "We have also shown that TNF-α, as the only inflammatory cytokine that directly influences the survival of patients with oral cancer, should be considered for further studies, possibly proving to be a predictor of prognosis of squamous cell carcinoma." (PMID 31870104, 2019). "We also found that TNF-α upregulated the expression of syncytin-1 in oral cancer cells and its receptor ASCT-2 in vascular endothelial cells, respectively." (PMID 31380426, 2019). "In summary, our sequencing findings establish TNFα as a significant promoter of cancer progression, modulating the gene expression in such a way that oral cancer cells decrease cell division and increase invasion." (PMID 30018735, 2018). "This article reviews the expression of levels of specific cytokines i.e., IL-8, IL-6 and TNF-α, their signaling pathways in the development of oral cancer, and how they are essential for the diagnosis of OSCC and updates related to it." (PMID 28397778, 2017). "Consistent with TNF-α being an upstream mediator for HAS3 expression, the expression of HAS3 was positively correlated with that of TNF-α in oral cancer specimens." (PMID 28107185, 2017). "Together, TNF-α induced the transcriptional regulation of HAS3 expression through a direct binding of activated NF-κB in oral cancer." (PMID 28107185, 2017). "Due to the inability of having specific HAS3 protein staining in clinical specimens, we, therefore, investigated the transcript levels of HAS3 and TNF-α in pairwise oral cancer specimens by using qRT-PCR." (PMID 28107185, 2017). "The increase of both HAS3 and TNF-α mRNA expression was correlated with decreased overall survival for oral cancer patients." (PMID 28107185, 2017). "Our present study demonstrates that the Wnt/β-catenin pathway activation-dependent up-regulation of syncytin-1 is involved in the pro-inflammatory factor TNF-α-promoted cell fusion between oral cancer and endothelial cells." (PMID 28112190, 2017). "HAS3 overexpression significantly increased oral cancer cell migration, invasion and xenograft tumorigenesis accompanied with the increased expression of tumor necrosis factor alpha (TNF-α) and monocyte chemoattractant protein 1 (MCP-1)." (PMID 28107185, 2017). "The expression of HAS3 or TNF-α mRNA was significantly increased in 86 oral cancer relative to adjacent normal tissues." (PMID 28107185, 2017). "This study confirmed for the first time that TNF-α with its downstream effector NF-κB activity is a potential inducer for HAS3 overexpression in oral cancer." (PMID 28107185, 2017). "TNF-α, frequently overexpressed in advanced oral cancer tissues, functioned as an upstream inducer for HAS3 transcriptional expression partly through NF-κB activation." (PMID 28107185, 2017). "TNF-α is upregulated in oral cancer tissues, as reflected in previous analyses of several inflammatory salivary cytokines in the saliva of oral cancer patients." (PMID 23634222, 2013). "Serum TNF-α was significantly higher in control subjects than in oral cancer patients.Conclusions: Patients with oral cancer have elevated levels of inflammatory cytokines in their saliva." (PMID 21743397, 2012).